TWIST1 (twist family bHLH transcription factor 1)
Diseases named in the same sentence as TWIST1 in open-access papers (continued):
Sharing a sentence is not in itself a finding about the gene and the disease.
cancer (continued). "However, in-depth research on TWIST1 and cancer stem cell differentiation is poorly reported." (PMID 36123378, 2022). "Hence, the ZEB2/TWIST1 co-repression of E-cadherin appears to be ubiquitous and crucial, providing potential targets for clinical diagnosis and therapeutical design for malignant carcinomas." (PMID 35884488, 2022). "In light of findings highlighting the role of Twist1 in tumorigenesis and metastasis, researchers have recently engineered a tamoxifen-controllable twist1a transgenic zebrafish as a novel animal model for the discovery of anti-metastasis drugs targeting the metastatic dissemination of cancer cells." (PMID 34577566, 2021). "Therefore, we predicted that SLUG or TWIST1 could contribute to TMPRSS4-mediated induction of cancer stem–like properties." (PMID 34809669, 2021). "Because the high expression level of Twist1 affects the responses to various chemotherapies in different types of cancer, the proper modulation or genetic ablation of Twist1 needs to be studied for the further possibility to restore sensitivity to the cancer drugs." (PMID 33768509, 2021). "A number of TWIST1 studies have shown the complex role of this TF in normal and disease states —it plays a significant role in organ development, including in the initiation of uterine decidualization, but it may also promote cancer metastasis." (PMID 34947922, 2021). "However, Twist1 is overexpressed across cancers with a well-established role in metastasis." (PMID 32337580, 2020). "However, the impact of Twist1 overexpression on chromosomal stability in the context of EMT in cancer cells remains unclear." (PMID 32337580, 2020). "Excess levels of Twist1 and the concomitant reduction in lamin levels may induce stemness in transformed cells and create ‘founder’ populations of cancer stem cells, with elevated genomic instability and resilient sub-populations of cancer cells." (PMID 32337580, 2020). "Moreover, Twist1 has been proved the role of enhancing metastasis in many types of cancers." (PMID 31931858, 2020). "Moreover, MAGE-A4 may be a direct target of TWIST1, which also up-regulates cell cycle progression, proliferation and migration and inhibits cell death in cancer and embryonic cells." (PMID 31143371, 2019). "In addition, LUADT1 may sponge miR-15a-3p to upregulate Twist1, thereby promoting cancer cell invasion and migration." (PMID 31842825, 2019). "For example, EMT/MET inducers, such as SNAIL1/2 or TWIST1/2, are associated with relapse and survival in several cancers, such as those that arise in mammary, colorectal, and ovarian tissues, suggesting that EMT/MET pathways are associated with poor outcomes of cancer patients." (PMID 30283976, 2019). "Finally, SNCG knockdown inhibits the promotion of cancer metastasis by Twist1." (PMID 29795373, 2018). "SNCG may promote cancer progression downstream of Smad-Twist1 axis in TGF-β signaling." (PMID 29795373, 2018). "In addition, evidence has shown that Twist1 can confer cancer cells stemness properties." (PMID 28099910, 2017). "However, we focused on the role of Twist1 in cancer-associated fibroblasts rather than cancer cells." (PMID 29029429, 2017). "Therefore, the regulation of TWIST1 expression in cancer cells might be a potential target for the suppression of cancer cell metastases." (PMID 27930738, 2016). "Bcl‐2 could form a complex with Twist1 to synergistically promote the transcription of downstream target genes, which can lead a cascade changes in proliferation, migration, metastasis and vasculogenesis in malignant tumours." (PMID 27027258, 2016).
cancer (continued). "In addition to E-cadherin downregulation, Twist1 may contribute to the development of a motile mesenchymal-like cancer cell phenotype through the activation of RAC1 (Ras-related C3 botulinum toxin substrate 1), a small G-protein of the Rho family." (PMID 27074574, 2016). "Thus, promoter methylation of TWIST1 gene might be one of the mechanisms of TWIST1 down-regulation by TQ, which might be a cancer-cell-specific mechanism." (PMID 26023736, 2015). "Interestingly, Twist1 can elicits cancer movement through activation of Rac1 GTPase." (PMID 25868853, 2015). "Analysis of human cancer datasets confirms that elevated WNT gene expression is associated with high levels of CUX1 and GLIS1 and correlates with genes of the epithelial-to-mesenchymal transition (EMT) signature: VIM, SNAI1 and TWIST1 are elevated whereas CDH1 and OCLN are decreased." (PMID 25217618, 2014). "In addition to inducing chemoresistant properties, TWIST1 also has a role in cancer angiogenesis." (PMID 25238494, 2014). "Thus, the model presented here, by which Twist1 represses neuronal cell identity in NCC derivatives, may ultimately shed light upon the role of TWIST1 in cancer." (PMID 23555309, 2013). "However, whether the highly conserved WR domain plays any roles in TWIST1-induced cancer metastasis is an open question." (PMID 22891766, 2012). "However, the molecular events triggered by TWIST1 to motivate dissemination of cancer cells are largely unknown." (PMID 22891766, 2012). "Therefore manipulation of Twist1-mediated regulatory events could be used to develop therapeutic strategies related to both human heart valve disease and cancer progression." (PMID 22242143, 2011). "However, since TWIST1 is strongly up-regulated in PCa samples it may still be useful as a cancer marker or therapeutical target." (PMID 20976069, 2010). "Of further interest, the link between EGFR mediated signaling and activation of TWIST1 in other cancers supports the intriguing possibility that this pro-invasive signaling network may activate specific micro-environmental changes in invasive GBM that correlate with specific MR imaging features." (PMID 20847921, 2010). "Given that TWIST1 promotes carcinoma invasion and metastasis through activation of EMT we sought to determine whether TWIST1 activated molecular features associated with carcinoma EMT in GBM cells." (PMID 20646316, 2010). "Importantly, TWIST1 over-expression generated cell phenotypes highly consistent with the over-representation of genes within these functional categories that reflect critical individual cellular features required for carcinoma and GBM invasion." (PMID 20646316, 2010). "For example, promoter methylation of TWIST1, an anti-apoptotic and pro-metastatic transcription factor, is significantly more prevalent in malignant breast tissue than in healthy breast tissue, and even more prevalent in metastatic lesions relative to matched primary cancers." (PMID 19995452, 2009). "Transcription factors such as Twist1 and ZEB1, which promote EMT and cancer metastasis, can increase the expression of LOX and LOXL2 by inhibiting miR-200, thereby enhancing collagen cross-linking and matrix stiffness." (PMID 40211368, 2025). "MØ-derived factors are also thought to act on cancer cells and to promote the typical features of EMT, including activation of pro-EMT transcription factors (Snail1, Twist1 and ZEB)." (PMID 40807456, 2025). "PELP1 modulates genes that are involved in the epithelial–mesenchymal transition (EMT), including MMPs, SNAIL (SNAI1), TWIST (TWIST1), ZEB (ZEB1), MYC, MTA1, miR-200a, and miR-141, leading to cancer metastasis progression." (PMID 41463382, 2025). "This ubiquitination marks Twist1 for degradation, which subsequently suppresses EMT processes, including cancer cell migration and invasion." (PMID 40521202, 2025).
cancer (continued). "Carcinogenesis stiffens the extracellular matrix (ECM) of cancerous tissues, to which cancer cells respond by activating transcription factors, such as YAP/TAZ, Twist1, and β-catenin, which further elevate their malignancy." (PMID 40124511, 2025). "Conversely, E3 ligase RNF8 146, RBX1147, and FBXO3 148 stabilize Twist1 to activate EMT and cancer progression." (PMID 41208892, 2025). "Twist1 significantly promotes the EMT pathway and cancer cell invasion, hence favoring cancer metastasis." (PMID 41373888, 2025). "CASC15, an oncogenic factor in tumorigenesis of various cancers including BrC, is known to promote EMT by increasing N-cadherin and vimentin protein levels while decreasing that of E-cadherin via TWIST1." (PMID 40943642, 2025). "In conclusion, SPOP's role in ubiquitinating and destabilizing Twist1 is crucial for controlling EMT levels and mitigating aggressive cancer behaviors." (PMID 40521202, 2025). "The upregulated ABCB1, ZEB1, and CD44 were engaged in microRNA regulation in cancer, SOX2 and KLF4 were engaged in pluripotency of stem cells, and TWIST1 and CD44 contributed to proteoglycans in cancer." (PMID 40251609, 2025). "The transcription factors regulating EMT, including snail family transcriptional repressor 1 (SNAI1), twist family bhlh transcription factor 1 (Twist1), zinc finger e-box binding homeobox 1 (ZEB1) and ZEB2, regulate cancer migration, invasion, and metastasis." (PMID 39154024, 2024). "Twist1 increases the expression level of circ-10,720 to upregulate vimentin, trigger EMT, and enhance cancer invasion." (PMID 38733529, 2024). "TWIST1, a transcription factor involved in EMT, promotes cancer cell migration and metastatic spread." (PMID 38252369, 2024). "TWIST1 is a member of the transcription factor family that promotes epithelial-mesenchymal transition (EMT), cell migration and cancer invasion." (PMID 39153052, 2024). "Meanwhile, abnormal expression of SOX5 can also promote cancer proliferation, invasion and Epithelial to Mesenchymal Transition (EMT) by targeting different downstream genes such as Twist1, Snail and acidic secreted protein rich in cysteine." (PMID 38835366, 2024). "For instance, a study utilizing a mouse model of skin cancer demonstrated that the activation of Twist1 induces EMT and facilitates the dissemination of cancer cells through the bloodstream." (PMID 38398197, 2024). "Conversely, in distant tissues, the downregulation of Twist1, which triggers the MET process, is necessary for the proliferation of disseminated cancer cells and the formation of macrometastases." (PMID 38398197, 2024). "The interaction of IL-1β with its IL-1 Type 1 receptor (IL-1R1) activates β-catenin-dependent signaling, upregulating TWIST1 and SNAIL1 and triggering the EMT program in cancer cells." (PMID 39201656, 2024). "Both proteins are classified as EMT-TFs and are frequently activated during carcinogenesis, with the majority of research focusing on the role of Twist1 in EMT and cancer metastasis." (PMID 39648980, 2024). "Mechanistically, circ-0001681 increases Twist1 expression via miR-942-5p sponging to induce EMT and cancer invasion." (PMID 38733529, 2024). "The role of Twist1 in promoting aggressiveness and EMT processes has been widely reported in cancer." (PMID 38835366, 2024). "Due to their central role in EMT and extensive studies in cancer, ZEB1, ZEB2, SNAI1, SNAI2 and TWIST1 are considered as the core EMT-TFs." (PMID 39164745, 2024). "EMT is associated with chromosomal instability and the EMT transcription factor TWIST1 induces chromosomal instability and the expression of the DNA damage marker H2AX in cancer cells." (PMID 39164745, 2024). "The analysis showed that TWIST1, RUNX1, CEBPA, and RELA were upregulated in carcinoma samples compared with normal renal tissues, whereas HIF1A was downregulated." (PMID 38724670, 2024).
cancer (continued). "Several studies have suggested TWIST1 involvement in epithelial-mesenchymal transition (EMT)-mediated metastasis and malignant transformation of cancer, and TWIST1 expression levels have been found to correlate with patient prognosis." (PMID 37534184, 2023). "Studies have shown that TWIST1 protein, an important transcription factor in the process of EMT transformation, plays an important role in the migration and invasion of cancer cells and can positively regulate the migration and invasion of cancer cells." (PMID 37115802, 2023). "When Zeb2 and Twist1 were both inhibited, the metastasis was markedly suppressed in a mouse CRC model, suggesting that Zeb2 and Twist1 contribute to cancer cell migration." (PMID 36768876, 2023). "These EMT-TFs, mainly including SNAILl, Twist-related protein 1 (TWIST1), ZEB1 and ZEB2, are pivotal in activating CAFs in different cancer contexts." (PMID 38124183, 2023). "EMT‐activating transcription factors, including Twist1, Snail, and ZEB family members, play a pivotal role in cancer progression." (PMID 36847128, 2023). "We therefore evaluated the expression of a panel of epithelial (KRT5, 7, 8, 18, and CDH1), mesenchymal (VIM, FN1, SNAI1, TWIST1, COL1A1, and PRRX1), and cancer stem cell (ALDH1A2, ALDH7A1, CD44, and CCND1) markers in all samples." (PMID 36980717, 2023). "Data also suggest that the polycomb group protein named B lymphoma Mo-MLV insertion region 1 homolog (Bmi1) is a downstream target of Twist1 and is crucial for EMT and cancer metastasis." (PMID 38002001, 2023). "We also observed differential expression of cancer-metastasis-inducing genes, such as ZEB1, MMP9, CLDN3, TWIST1 and N-cadherin, between LVI(+) and LVI(−) samples in some patients, indicating a correlation of VCAN with EMT genes in LVI(+) samples." (PMID 37108649, 2023). "A key way how p38 promotes EMT in cancer cells is by stabilizing and increasing the function of some of the EMT core transcription factors such as SNAIL, ZEB1, and TWIST1." (PMID 37009481, 2023). "Cancer cells cocultured with adipocytes increase the levels of EMT-inducing transcription factors FOXC2 and TWIST1 in a HIF-1α adipocyte expression-dependent manner." (PMID 36670988, 2023). "In Caco2 cells, platelet-derived mEVs from CRC-induced TWIST1 (at 4 and 24 h) and VIM (at 4 and 24 h) while downregulating CDH1 (at 24 h) vs. cancer cells cultured alone." (PMID 36672299, 2023). "Meanwhile, the critical transcription factors, including TWIST1, TWIST2, ZEB1, ZEB2, SNAI1 and SNAI2, participate in the EMT process, leading to cancer cell migration and invasion." (PMID 37794509, 2023). "Twist1, a transcription regulator during embryonic development, is an important driver of EMT and a key regulator of metastasis in cancer." (PMID 36980876, 2023). "Studies have shown that Twist1 binds to other bHLH dimers and regulates the transcription of EMT-related genes, and is involved in the metastasis of various cancers." (PMID 36639679, 2023). "Novel research in HNSCC has revealed that the overexpression of Twist1 is essential for suppressing E-cadherin expression in cancer cells, inducing EMT, and thereby imparting cancer epithelial cells with stem cell properties, which help maintain CSC stemness." (PMID 37853437, 2023). "We showed that platelet-derived EVs from CRC patients induced TWIST1 and VIM in all the cancer cell lines studied, while platelet-derived EVs from HS did not." (PMID 36672299, 2023). "In HT29 cells, platelet-derived mEVs from CRC significantly induced TWIST1 (at 4 h) and VIM (at 4 and 24 h) vs. cancer cells cultured alone." (PMID 36672299, 2023). "The activation of the PI3K-AKT-GSK3β pathway downstream of ROR1 is known to promote EMT by increased expression of mesenchymal markers Snail, Twist1, and MMP9, which all play a significant role in the migration and invasion of cancer." (PMID 38213538, 2023).
cancer (continued). "Activated ISX then enhanced EMT marker expression—including TWIST1, Snail 1, and VEGF—and consequent cancer metastasis, but suppressed E-cadherin expression." (PMID 37444447, 2023). "Whereas SNAI1 was equally expressed or slightly downregulated in the partial-EMT subgroups of basal-like cancers, ZEB1, ZEB2, and TWIST1 were more highly expressed in cluster 1 that is defined by the EMT-up genes." (PMID 38111531, 2023). "TWIST1, a key transcriptional factor of epithelial‐mesenchymal transition (EMT), contributes to self‐renewal of cancer stem‐like cells (CSCs), chemo‐resistance, metastasis, and TNBC‐related death." (PMID 36782089, 2023). "On the other hand, SIRT3 inhibits the Wnt/β-catenin pathway and, indirectly, Twist1, Twist2, and Snail2, which are tightly connected with EMT progression, cancer invasion, and metastasis." (PMID 35745656, 2022). "Although expressions of 9 hyper-methylated genes were significantly different across cancer stages in the TCGA cohort, reduced expressions with increased cancer severity were observed for 3 hyper-methylated genes- SLITRK3, FOXE1, and TWIST1." (PMID 36329447, 2022). "We have also examined the levels of the EMT-TFs such as TWIST1, SNAIL, SLUG, ZEB1, and ZEB2 because targeting these factors has been suggested as potential cancer therapeutics." (PMID 35774120, 2022). "The upregulation of TWIST1 in HCC cell lines promotes the proliferation, cell migration, invasion, and metastasis of cancer cells." (PMID 35052775, 2022). "The genes Twist1 and Twist2 have both been shown to play a role in the promotion of EMT and invasion in cancer." (PMID 35804837, 2022). "The transcription factors Twist1 and ZEB1 are powerful oncogenes that promote EMT and cancer metastasis." (PMID 35331296, 2022). "For example, ERK1/2 signaling promotes cancer cell migration, invasion, and EMT by mediating the expression or the transcriptional activity of EMT-inducing transcription factors Twist1, Snail, and Slug." (PMID 35589683, 2022). "Overexpression of EMT-master transcription factors including TWIST1, SNAIL, and SLUG promotes cancer-reprogramming processes in differentiated cells leading to a CSC-like status." (PMID 36474162, 2022). "TWIST1, as a bHLH transcription factor oncogene, is involved in the epithelial–mesenchymal transition (EMT) process in both embryonic and cancer development." (PMID 36553636, 2022). "An interesting study by Lai and colleagues showed that EMT and cancer stemness properties can be obtained upon chronic treatment with TNF-α, a pro-inflammatory cytokine that activates Twist1 in a NF-κB-dependent fashion." (PMID 36669020, 2022). "After confirming the TWIST1 gene overexpression in KYSE-30 cells, we assessed the mRNA expression profile of specific cancer stem cell self-renewal genes consequently." (PMID 36553636, 2022). "The over-expression of TWIST1 induces epithelial-mesenchymal transition (EMT), a key process in cancer metastasis." (PMID 35865633, 2022). "In cocultures of platelets and colorectal HT29 cancer cells, platelet-derived PGE2 upregulated TWIST1 via the activation of the EP4 receptor (one of the four PGE2 receptors)." (PMID 35308229, 2022). "Formation of filopodia downstream of activation of TWIST1 and SNAIL1 and the expression of formins regulate the migration of cancer cells undergoing EMT." (PMID 35203300, 2022). "TWIST1 is thought to be involved in EMT initiation in various pathological environments, involving cancer." (PMID 35802537, 2022). "TWIST1 also co-purified with NuRD complex, including MTA2, HDAC2, and RbAp48 in SW480 cells, which is consistent with previous findings in other cancer cell lines." (PMID 35884488, 2022). "TWIST1, as a known EMT marker in cancer, can trigger the generation of a CSC status through the overexpression of stemness markers in different types of cancers." (PMID 36553636, 2022).